Y_RNA (Y RNA )
Gene: Miscellaneous RNA gene on chromosome 20 (18,113,467 to 18,113,579, reverse strand). Ensembl gene ENSG00000207282.
Homologues: Orthologues: macaque Y_RNA (96% identical). Paralogues in human: RNY1 (94% identical), Y_RNA (91% identical), Y_RNA (90% identical), Y_RNA (89% identical), Y_RNA (88% identical), RNY1P11 (88% identical), Y_RNA (87% identical), Y_RNA (86% identical), RNY1P7 (85% identical), RNY1P8 (85% identical), Y_RNA (85% identical), Y_RNA (84% identical), and 100 more.